RYR2 (ryanodine receptor 2)
Diseases named in the same sentence as RYR2 in open-access papers (continued):
Sharing a sentence is not in itself a finding about the gene and the disease.
Arrhythmia (continued). "A series of studies by Marks and colleagues have shown that FKBP12.6 mediates cardiac arrhythmia, heart failure, and sudden cardiac death, which are attributed to dysfunction of the mechanism of RyR2 inhibition by FKBP12.6." (PMID 32669538, 2020). "Recent research in humans and mouse models carrying RyR2 mutations associated with CPVT shows coincidence of CPVT, seizures and SUDEP, suggesting a possible connection between the induction of cardiac arrhythmias and irregular CNS activity." (PMID 32742694, 2020). "The increased diastolic Ca2+ leak observed in Wt-Nx mice is potentially a good substrate for the induction of cardiac arrhythmias since the released Ca2+ diffuses to neighboring RyR2 clusters inducing SCR and triggering cardiac arrhythmias." (PMID 33238586, 2020). "The resulting increase in diastolic Ca2+ levels was found to recruit CaMKII, which in turn phosphorylated RYR2 to induce an increase in SR Ca2+ leakage, spontaneous Ca2+ sparks, and resultant arrhythmias." (PMID 31426283, 2019). "Henceforth, RyR2 represents the central target of many pathways dysregulated in cardiac pathological conditions, including arrhythmia, heart failure, metabolic disorders." (PMID 31143551, 2019). "We validated and optimized the NGS platform with a subset of 46 patients by comparison with Sanger sequencing of coding exons of major arrhythmia risk-genes (KCNQ1, KCNH2, SCN5A, KCNE1, KCNE2, RYR2)." (PMID 31337358, 2019). "The detrimental effect of RyR2 activation (i.e., arrhythmias and cardiac damage) can only take place when it occurs associated to an increase in SR Ca2+ uptake, able to maintain SR Ca2+ leak." (PMID 32038301, 2019). "What’s more, cAMP can activate both protein kinase A (PKA) and the exchange protein directly triggered by cAMP (Epac) which mediates β1-AR-induced arrhythmia via CaMKII or RyR2 phosphorylation, and activates LTCC." (PMID 31822281, 2019). "Ryanodine receptor 2 (RyR2) plays an important role in maintaining the normal heart function, and mutantions can lead to arrhythmia, heart failure and other heart diseases." (PMID 31143551, 2019). "Arrhythmias in CPVT are induced by spontaneous RYR2-mediated Ca2+ release, which stimulates DADs to induce extrasystolic beats." (PMID 31426283, 2019). "CaM inhibits RyR2 in a Ca2+-dependent manner and aberrant CaM-dependent inhibition results in life-threatening cardiac arrhythmias." (PMID 30530841, 2019). "In the study by Itzhaki and coworkers with a M4109R RYR2 mutant iPSC-derived CMs, DADs in the phase 4 of APs were the most prevalent arrhythmias seen in patch-clamp recordings." (PMID 29760739, 2018). "A large amount of evidence, obtained in humans and animals, shows that oxidized RyR2 produces arrhythmias." (PMID 29439404, 2018). "The findings are thus consistent with acute pro‐arrhythmic actions of RyR2 receptor modulation on both CV and arrhythmia, adding to previous studies implicating chronic alterations in Na+ channel protein expression reported with genetic modifications of RyR2." (PMID 28316073, 2017). "Together these findings suggest actions of Epac‐mediated RyR2 activation by 8‐CPT both increases the incidence of arrhythmia following extrasystolic, and incremental pacing and reduces CV without affecting AP recovery properties." (PMID 28316073, 2017). "The results are consistent with GSTM2C entering the myocytes and inhibiting RyR2, in a manner that indicates a possible therapeutic potential for treatment of arrhythmia in the neonatal heart." (PMID 27612301, 2016). "Genetic ablation of CaMKII-dependent RyR2 phosphorylation in the S2814A mouse provides protection from pacing-induced arrhythmias after pressure-overload, slows the development of contractile dysfunction, and reduces ventricular remodeling and cellular SCR." (PMID 24994983, 2014). "The autosomal dominant form of CPVT has become the prototypical disease of RyR2-mediated arrhythmia, and accounts for at least half of all positive CPVT diagnoses." (PMID 24994983, 2014).
Arrhythmia (continued). "Given its relative high prevalence and potential importance in the pathogenesis of cardiac arrhythmias and cardiomyopathies, we have attempted to generate a mouse model for the human RyR2 exon-3 deletion." (PMID 24743769, 2014). "In accordance with this notion, slowing of the termination of RyR2 calcium release has been reported in patients prone to arrhythmia." (PMID 23390511, 2013). "Taken together, the RyR2-dependent SR Ca2+ leak has emerged as a pivot in the development of cardiac arrhythmias as well as heart failure under various conditions and therefore represents a promising toehold for future therapies." (PMID 22932727, 2013). "Although not experimentally shown, it has previously been suggested that CPVT patients with RyR2 mutations are susceptible to both EAD and DAD-mediated arrhythmia mechanisms." (PMID 22962621, 2012). "CPVT results from various mutations of RyR2 that may go undetected until physical or emotional stressors augment pre-existing Ca2+ handling dysfunction, causing acute responses characterized by arrhythmias with the potential of degenerating into ventricular fibrillation." (PMID 20668646, 2010). "Arrhythmias and seizures were observed in 12 cases of CPVT affected by RYR2 gene mutation." (PMID 41062843, 2026). "RyR2 clusters progressively disperse during β-AR overactivation due to channel phosphorylation by PKA, diminishing the decreased efficiency of CICR, which implicates an important meaning for HF and other diseases with a risk of arrhythmia." (PMID 40072053, 2025). "Thus, it is found that RyR2 stabilization therapy is effective in preventing LV remodeling and fatal arrhythmia for HF induced by MI in mice." (PMID 40072053, 2025). "Pini Radix in Poria, a parasitic herb used in traditional Chinese medicine mainly for palpitations and amnesia, attenuated BaCl2‐induced cardiac arrhythmia damage by suppressing RyR2 expression and reducing adrenaline and cAMP through the adrenergic signaling pathway." (PMID 40202070, 2025). "One mechanism implicated in IPC-mediated cardioprotection is a decrease in Ca2+ release from the SR via the type 2 ryanodine receptor (RyR2) upon reperfusion, which lowers mitochondrial Ca2+ levels and potentially also explains the reduction in reperfusion-induced arrhythmias observed with IPC." (PMID 38890208, 2024). "Another study found an association between missense variants in Ryr2 and epilepsy with or without arrhythmia." (PMID 38444585, 2024). "Thus, extrasystolic, S2, stimulation provoked arrhythmia at longer S1S2 intervals in the RyR2-P2328S that nevertheless corresponded to similar (dV/dt)max, and effective interatrial CVs as those provoking arrhythmia in WT." (PMID 37122213, 2023). "Previous studies have demonstrated an association between RYR2 polymorphisms and arrhythmias; however, no study has evaluated bleeding complications." (PMID 38034995, 2023). "The results suggested that RYR2-A1855D and SCN10A-1362H double variants may increase the susceptibility of cardiomyocytes to arrhythmias." (PMID 37122207, 2023). "As RyR2 activation by halothane was strongly inhibited by a physiological concentration of cytosolic Mg2+, a situation to occur in diastole, it is unlikely to play a significant role in commonly observed anesthetic-induced cardiac arrhythmias." (PMID 36982484, 2023). "I reasoned that since heart failure was well known to be a chronic hyperadrenergic state and was highly associated with cardiac arrhythmias, there might also be PKA phosphorylation of RyR2 channels in failing hearts." (PMID 36647824, 2023). "One way for cardiac arrhythmias to occur is through “leaky” ryanodine receptors (RYR2)." (PMID 37887414, 2023). "Here, we identify another potential mechanism that could be increasing the risk of arrhythmias and SCD, i.e., the disruption of the opening and closing of RyR2 by HIV-Tat and select antiretroviral drugs." (PMID 36613717, 2022).
Arrhythmia (continued). "However, determination of the specific roles of phosphorylation of RyR2 (Ser2808) and RyR2 (Ser2814) in arrhythmia requires further investigation." (PMID 36225189, 2022). "Isoproterenol treatment has also been demonstrated to result in delayed afterdepolarizations (DADs) and arrhythmias in conditional RyR2 KO mice resulting in a 50% decrease in RyR2 expression, significantly decreasing the beat rate and cardiac output (ml/min) in comparison to wild type controls." (PMID 35620470, 2022). "However, the effects of this interaction on Ca2+ buffering and thus activity of RyR2 and cardiac arrhythmias are yet to be elucidated." (PMID 36425292, 2022). "Myomesin-2 may also interfere in cardiomyocytes with the ryanodine receptor type 2 (RYR2), a protein essential for Ca2+ release in heart as well as in cardiac arrhythmias." (PMID 35255917, 2022). "RyR2 is also a critical player in the pathogenesis of cardiac arrhythmias." (PMID 35233070, 2022). "However, only two knockin models were confirmed to exhibit exercise-triggered VTs, RyR2-R2474S+/– and RyR2-R4496C+/–, and are hence reminiscent of the human arrhythmia phenotype diagnosed by exercise stress testing." (PMID 34955889, 2021). "The arrhythmia-linked R176Q mutation within the β8–β9 loop decreases N-terminus tetramerization but does not affect RyR2 subunit tetramerization or the N-terminus interaction with C-terminus." (PMID 32077934, 2021). "However, the relative contribution of these calcium-handling alterations (Cx43-permeability and RyR2 calcium leak) to arrhythmia initiation, as well as the modulatory role of BARS in this model remain incompletely understood." (PMID 34630150, 2021). "Furthermore, we reported that cardiac arrhythmias in mdx mice can be prevented by stabilizing cardiomyocytes RYR2 channels with S107." (PMID 34884796, 2021). "Overall, these observations have led to a general belief that disease-linked RyR2 mutations cause GOF defects, leading to inappropriate activation of the channel and excessive SR Ca2+ release that can precipitate into cardiac arrhythmias, cardiomyopathies, or sudden death." (PMID 33825858, 2021). "Incubation of ISO-challenged CPVT VMs with mitoTEMPO restored SR Ca2+ content and reduced spontaneous Ca2+ release, which implies that oxidation of RyR2 secondary to genetically evoked gain of function of SR Ca2+ release plays a key role in Ca2+-dependent arrhythmia." (PMID 32444920, 2020). "Thus, dysfunction and modification of RyR2 have received much attention as potential targets for prevention of arrhythmias in HF." (PMID 33569394, 2020). "If ET is to be used as an antiarrhythmic intervention, negative effects on systolic Ca2+ release responsible for contraction should not outweigh the positive effects of ET on RyR2-dependent spontaneous Ca2+ release associated with arrhythmias." (PMID 33569394, 2020). "Based on these results, we speculate that a cardiac arrhythmia due to the identified RyR2 sequence alteration (p.K4056N) might have contributed to the death in our SUD victim." (PMID 32101375, 2020). "The role of RyR2 remodeling in brainstem nuclei remains unknown but might be involved in cardiac and respiratory dysfunction, such as arrhythmias and diaphragm muscle weakness in HD." (PMID 32897880, 2020). "For instance, genetic autopsies have revealed gain-of-function mutations in sodium channels (Nav1.5) and type 2 ryanodine receptors (RyR2) as well as loss of function in potassium channels (Kv7.1, hERG), which are common to both sudden unexplained death in epilepsy (SUDEP) and cardiac arrhythmias." (PMID 32742694, 2020). "We hypothesized that the RyR2 remodeling in NA and C1 neurons could induce a sympathovagal imbalance contributing to cardiac arrhythmias." (PMID 32897880, 2020). "More recent experiments indicated that a change in RyR2 may be also involved in cardiac glycosides–induced arrhythmias." (PMID 32038301, 2019).
Arrhythmia (continued). "MiR-1 is the most abundant microRNA in the adult mouse heart, accounting for 35–40% of the total amount of miRNA MiR-1 directly targets connexin-43, KcnJ2, Kcne1, Ncx1, PP2A/RyR2, and Hcn4 in the adult heart, contributing to the arrhythmias that we and others observed in miR-1 TG adult hearts." (PMID 30936836, 2019). "Furthermore, both carvedilol and flecainide were the most effective in abolishing arrhythmias in CMs carrying RYR2 exon 3 deletion." (PMID 29760739, 2018). "Therefore, using this model, we studied the response to cytoplasmic calcium of single RyR2 channels incorporated in planar bilayers and quantified the occurrence of spontaneous arrhythmias through electrocardiogram (ECG) recordings." (PMID 29439404, 2018). "Indeed, dysregulation of Ca2+ channels and RyR2 can result in life-threatening cardiac arrhythmias, both in hereditary cardiac arrhythmia syndrome or acquired heart diseases." (PMID 29549309, 2018). "It should be noted that RyR2‐independent effects of statins may also contribute to their ability to protect against cardiac arrhythmia." (PMID 29278865, 2018). "The significance of the question is not only basic, but also lies in the potential use of GSTM2C or its derivatives as drugs to reduce excess Ca2+ release in juvenile cardiomyopathies with arrhythmia attributed to high diastolic Ca2+ levels due to excess Ca2+ leak through RyR2." (PMID 27612301, 2016). "On the other hand, it has been reported that hypo-nitrosylation and increased oxidation of RyR2 (that further increase RyR2 open probability) in pathological conditions that impose chronic oxidative stress may lead to diastolic Ca2+ leak and arrhythmia." (PMID 27529477, 2016). "Our results suggest that similar mechanisms may be at play in human AF as well, since increased propensity to CDA driven by RyR2 dysfunction led to increased arrhythmia vulnerability, complexity, and persistence in our model." (PMID 27812021, 2016). "To date, our study is the first one to analyze the possible role of RyR2 Q2958R polymorphism in SCD, showing that it might contribute to the onset of malignant cardiac arrhythmias." (PMID 26904356, 2016). "Inhibition of Rac1 decreases ROS production, RyR2 oxidation, and cardiac arrhythmia during I/R." (PMID 27222313, 2016). "In bilayer studies, experimental removal of CSQ2 from RyR2 increases the sensitivity of RyR2 to changes in luminal Ca2+, in a manner that could lead to arrhythmia." (PMID 25609705, 2015). "Consequently dysfunction in the release of Ca2+ and modulatory influences that control RyR2 function are identified as contributory to the pathophysiology of heart failure and fatal cardiac arrhythmias." (PMID 26041778, 2015). "RyR2 is also a critical player in the pathogenesis of cardiac arrhythmias and cardiomyopathies." (PMID 26405799, 2015). "RyR2 is also a key player in the pathogenesis of cardiac arrhythmias and cardiomyopathies." (PMID 24743769, 2014). "On one hand, CaMKII phosphorylation is presumed to increase RyR2 activity and promote SR Ca2+ leak that, when excessive, may trigger cardiac arrhythmias." (PMID 24847270, 2014). "This review centres upon the role of the cardiac RyR2 isoform in arrhythmia and SCD." (PMID 19345240, 2009). "In addition, these data further support a role for the primed state of RyR2 in HF and arrhythmias." (PMID 39278969, 2024). "In both systems, the effects of PDE4B ablation on arrhythmia susceptibility could also potentially originate from both altered regulation of the LTCC complex and from direct effect on the local cAMP levels at and the leakiness of RyR2." (PMID 38534320, 2024). "Many of these mutations encode a leaky RyR2 channel, predisposed to spontaneous Ca2+ release, particularly under conditions of heightened catecholaminergic activity, such that exercise and/or emotional stress may result in fatal cardiac arrhythmias due to RyR2-related Ca2+ leak." (PMID 39278969, 2024).
Arrhythmia (continued). "Thus, exposure to BaCl2 in zebrafish, Ba2+ promotes the secretion of adrenaline, that might generate abnormal metabolic signals, leading to increased RyR2 expression and result in arrhythmia." (PMID 37598173, 2023). "Furthermore, cardiac-specific RYR2 transgenic mice have bradycardia and arrhythmias." (PMID 37887414, 2023). "Also, arrhythmias in iPSC-CM carrying RyR2-R420Q and CASQ2-D307H, evoked by isoproterenol, a synthetic catechol compound, or even sometimes pacing alone, were associated with an elevation in the resting level, probably resulting from a prominent diastolic intracellular Ca2+ rise." (PMID 35399287, 2022). "Otherwise, simply enhancing adrenergic signaling without correcting RyR2 dysfunction (like β-AR agonists) may exacerbate RyR2 dysfunction and Ca2+ leak, increasing the arrhythmia risk and sudden cardiac death in HF." (PMID 35845057, 2022). "Our results suggest that the ability of calmodulin to discriminate between RyR1 an RyR2 targets depends on kinetic discrimination and robust allosteric communication between Ca2+-binding sites (EF1-EF3 and EF3-EF4 pairs), which is perturbed in both N97I and Q135P arrhythmia-associated variants." (PMID 36685279, 2022). "Furthermore, it has been proposed that CaMKII‐dependent phosphorylation of RyR2 might even be necessary for β‐adrenoceptor stimulation‐induced arrhythmias in CPVT." (PMID 34558218, 2021). "The predicted impact of small RyR2 clusters on diastolic leak, and therefore the susceptibility to arrhythmia, critically depends on the presence or absence of direct coupling between cardiac RyR2 channels, which is currently still a topic of debate in Ca2+ signaling physiology." (PMID 33718369, 2021). "Therefore, we injected RyR2-PBmice with epinephrine and caffeine to further determine whether these stimulants could induce arrhythmias or other heart diseases." (PMID 31143551, 2019). "Therefore, since statins are given to patients with a history of heart disease and an increased likelihood of experiencing arrhythmias, it is important to investigate whether statins also affect cardiac RyR2 channel function." (PMID 29278865, 2018). "Our top candidates included previously known modifier genes (FHOD3), a gene known to cause DCM and HCM when mutated (TTN) and genes associated with related cardiovascular phenotypes such as heart failure (HNRNPC) and arrhythmia (CACNA1C, RYR2)." (PMID 40791945, 2025). "Type-2 ryanodine receptor (RyR2) is the major Ca2+ release channel of the cardiac sarcoplasmic reticulum (SR) that controls the rhythm and strength of the heartbeat, but its malfunction may generate severe arrhythmia leading to sudden cardiac death or heart failure." (PMID 37894987, 2023). "In particular, RyR2, CACNA1S, and CACNA1S were highly enriched and identified as prominent targets in arrhythmia treatment among these three pathways." (PMID 37598173, 2023). "Impairment of the interaction between RyR2 and the 12.6-kDa FK506 binding protein (FKBP12.6) is also an important mechanism of arrhythmia." (PMID 36225189, 2022). "Thus, in the presence of RyR2 dysfunction and Ca2+ leak in HF, β-ARs desensitization/down-regulation, by diminishing adrenergic signaling, helps to attenuate RyR2 dysfunction and Ca2+leak, protecting the heart from developing serious cardiac arrhythmias and sudden cardiac death." (PMID 35845057, 2022). "For this purpose, arrhythmias were studied in RyR2‐RS/MMVV, RyR2‐RS, and WT mice following i.p. administration of 20 mg/kg isoprenaline." (PMID 34558218, 2021). "Remodeled RyR2 in brainstems contributes to altered HRV and cardiac arrhythmias in a murine model of HD." (PMID 32897880, 2020).